WIPI1 (WD repeat domain, phosphoinositide interacting 1)
Diseases named in the same sentence as WIPI1 in open-access papers (continued):
Sharing a sentence is not in itself a finding about the gene and the disease.
vitiligo (1 paper, 2018). Generalized well circumscribed patches of leukoderma that are generally distributed over symmetric body locations and is due to autoimmune destruction of melanocytes. "To determine if WIPI1 downregulation in vitiligo skin can be associated with impaired autophagy in melanocytes, we stained the tissue sections of skin biopsy samples for microtubule-associated protein light chain 3 (LC3)." (PMID 30515176, 2018). "Therefore, in vitiligo skin, WIPI1 downregulation may be rather linked with impaired maturation of melanosomes and not with impaired autophagy." (PMID 30515176, 2018). "According to our data, downregulation of WIPI1 in vitiligo skin and activation of autophagy are uncoupled processes as WIPI1 expression was reduced to a similar degree in lesional and non-lesional skin whereas LC3 staining clearly indicated increased autophagy only in keratinocytes of lesional skin." (PMID 30515176, 2018). "However, this is unlikely regarding the reduced WIPI1 expression in vitiligo non-lesional skin." (PMID 30515176, 2018).
infection (12 papers, 2012 to 2025). The state of being infected such as from the introduction of a foreign agent such as serum, vaccine, antigenic substance or organism. "After an infection period of 2 h, 40–50% of the cells harbored WIPI-1 positive autophagosome-like vesicles sequestering agr-positive S. aureus (USA300, HG001), and 20% of the tumor cells contained entrapped agr-negative S. aureus (SA113)." (PMID 22829830, 2012). "We also tested whether several host autophagy-related components, including Atg1 (ULK1), Atg2, Atg18 (WIPI1), Atg9 and Beclin 1, conferred susceptibility to Bm16M infection via CFU assay and image-based host cell infection analysis." (PMID 29732320, 2018). "Many genes in the autophagy and mitophagy signaling pathways, such as ULK2, BNIP3, WIPI1 and CTSB, presented significantly upregulated expression profiles following infection." (PMID 39650642, 2024). "Levels of WIPI1 and Beclin-1 expression were increased by the autophagy inducer torin but were no different in SFV-infected cells early in infection." (PMID 40042894, 2025).
tumor (11 papers, 2012 to 2025). "Time course experiments showed that the number of tumor cells that contain such WIPI-1 positive autophagosome-like vesicles with entrapped S. aureus cells increased over time (30 min–2 h)." (PMID 22829830, 2012). "Zhao and colleagues demonstrated that expression of WD repeat domain phosphoinositide-interacting protein 1 (WIPI-1) was reduced in NPC cells and tumour tissues." (PMID 40805271, 2025). "The results showed that TRAF3IP3, WIPI1, ARHGAP11A, and RHOQ were significantly differentially expressed in normal and tumor tissue, displaying good classification performance." (PMID 36185204, 2022). "The average expression levels of VPS45, WIPI1, TTC1, IGBP1 and KLHL21 genes in all tested HCC tissues were greatly increased compared with those in the adjacent non-tumor tissues, showing the similar results to microarray data." (PMID 27769251, 2016). "Furthermore, the WIPI1 expression and the ratio of LC3-II/LC3-I were dramatically increased, while the expression of p62 was decreased in tumor samples of the gefitinib + miR-450a-5p NC group." (PMID 32820249, 2020).
cancer (4 papers, 2016 to 2022). A tumor composed of atypical neoplastic, often pleomorphic cells that invade other tissues. "We then addressed the question of what cancer types show the most significant and relevant WIPI1 upregulation." (PMID 30622661, 2018). "The genes ITGA3, HSPA8, CTSD, ATG12, CLN3, ATG7, and MAP1LC3C negatively influenced patient survival, whereas WIPI1 may protect the patients from cancer-related death." (PMID 35186475, 2022). "One of these modifications is H3K9me2, which is carried out by the methyltransferase EHMT2 that represses the transcription of LC3, WIPI1, DOR, and BNIP3 in cancer cells." (PMID 27174920, 2016).
WIPI1 also shares sentences with these, for which no sentence is quoted: cardiac hypertrophy (2 papers); diabetes (2); neuroblastoma (2); phospholipidosis (2); prostate carcinoma (2); arrhythmogenic right ventricular cardiomyopathy (1); atransferrinemia (1); breast carcinoma (1); cervical cancer (1); dilated cardiomyopathy (1); Encephalocele (1); Encephalopathy (1); hemochromatosis (1); Hyperinsulinemia (1); hypertrophic cardiomyopathy (1); lung carcinoma (1); myeloma (1); nasopharyngeal carcinoma (1); nematode infection (1); neuronal ceroid lipofuscinosis (1); Obesity (1); pancreatic cancer (1); progeria (1); protein folding disorders (1); spina bifida (1); staphylococcus aureus infection (1); steatosis (1); tuberculosis (1); uveal melanoma (1).